MYC (MYC proto-oncogene, bHLH transcription factor)
Diseases named in the same sentence as MYC in open-access papers (continued):
Sharing a sentence is not in itself a finding about the gene and the disease.
cancer (continued). "We concluded that MYCMI-6 was well tolerated by the normal human cells at a concentration that was highly toxic to MYC-dependent tumors cells, showing good discrimination between cancer cells and normal cells in response to MYCMI-6 resulting in a good therapeutic window for this compound." (PMID 29968736, 2018). "Our findings suggest that the metabolic modulation and ROS augmentation could be used as novel strategies in treating NBL and other MYC-driven cancers." (PMID 29445162, 2018). "Indeed, the combination of drugs induced a significantly stronger downregulation of MYC than the individual drugs in most cancer cell lines tested, and in some cell lines, MYC was virtually eliminated after co-exposure." (PMID 29899872, 2018). "c-MYC is upregulated in many cancers, and is frequently involved in cancer pathogenesis." (PMID 30237861, 2018). "However, in recent studies, the MYC-independent mechanisms of JQ1 have been reported in several cancers." (PMID 29796168, 2018). "USP28 can counteract the activity of FBW7 and promote c-MYC stability in cancer cells." (PMID 29415985, 2018). "Our studies suggest that metabolic modulation of glutaminolysis and ROS augmentation may represent effective strategies in treating NBL and other MYC-driven cancers." (PMID 29445162, 2018). "A defect in MYC translation could lead to global gene expression changes because MYC is the primary transcription factor in cancer cells." (PMID 30103560, 2018). "Furthermore, c-MYC is overexpressed in 30% of all human cancers and frequently predicts poor clinical outcomes." (PMID 30237861, 2018). "Finally, many investigators are attempting to identify drugs that target MYC for the treatment of cancer." (PMID 30458889, 2018). "One example is that METTL3 modulates nn n zSP1, an oncogene in several cancers which regulates c-MYC expression in this way, identifying a new paradigm for selecting RNAs to be modified, namely the stable recruitment of the RNA-modifying enzyme to specific genomic loci." (PMID 29587823, 2018). "The alternative strategies of targeting MYC-driven cancers via selective inhibition of cellular pathways, like metabolism, that may selectively kill MYC-overexpressing cells have attractive therapeutic potential." (PMID 30459529, 2018). "Another example is PVT1, a lncRNA near MYC, which is a developmental gene involved in most cancers." (PMID 30305026, 2018). "In this review we focus on the MYC transcription factor network (also known as the MAX-MLX Network or the Extended MYC Network) which has been strongly implicated in normal cell growth and proliferation and in the etiology of a wide range of cancers." (PMID 30054853, 2018). "Comparison of effects of MYC and Tip60 knockdown on MTcoR panel gene expression in different cell lines suggests that there are genes co-regulated by MYC and the NuA4 complex in many cancer cell lines, as well as genes co-regulated by MYC and the NuA4 complex in a cell type-specific manner." (PMID 30108681, 2018). "Finally, as the HD753 sample harbors two previously characterized amplifications in the MET and MYC cancer drivers, both of which are present in the 130-gene assay, we assessed the performance of the 130-gene panel in identifying CNAs." (PMID 29354287, 2018). "Importantly, the stabilization of MYC mRNA by CRD-BP accounts for the increased mRNA stability observed in human cancers." (PMID 30597997, 2018). "With these caveats in mind, interruption of MYC-dependent pathways and MYC regulatory units might be a promising alternative to indirectly target MYC proteins in cancer." (PMID 29511348, 2018). "A well-known oncogene, c-MYC was reported to regulate Nampt expression in cancer cells." (PMID 30631755, 2018). "If MLXIP-MLX functions to suppress stress in MYC-driven cancers we might anticipate its involvement in other forms of stress response." (PMID 30054853, 2018). "c-MYC contributes to chemoresistance of cancer in part by controlling metabolism." (PMID 30603053, 2018).
cancer (continued). "The unique activity profile of tubacin identified here suggests that it may be effective as a therapeutic agent in not only FGFR3-dependent cancers, but other cancers in which cyclin D1 and/or MYC dysregulation are drivers." (PMID 29423038, 2018). "The primary function of the MTcoR panel of genes in DNA replication and cell cycle suggests that the MTcoR panel may be of potential importance for cancer therapies targeting MYC and the NuA4 complex." (PMID 30108681, 2018). "This looping was not limited to cancer cells, because examination of enhancer and promoter-capture Hi-C data in a variety of normal cell types that express MYC revealed that cell-type-specific enhancers do indeed loop to the MYC proximal CTCF site." (PMID 29641996, 2018). "Particularly, BRD4 is required for the expression of MYC, an oncogenic driver in many cancers." (PMID 30304769, 2018). "Human c-Myc protein (hereafter Myc) is a nuclear transcription factor encoded by the MYC gene that is found at locus 8q24.21 in a broader region on chromosome 8, which is frequently amplified in cancers." (PMID 30597997, 2018). "As c‐MYC has been shown to play a role in cancer therapy drug resistance, we investigated whether AXL‐dependent epirubicin resistance involves regulation of c‐MYC expression in EAC cells." (PMID 30353671, 2018). "Thus, hindering not only mt-rRNA transcription, but also mitoribosome function in MYC-overexpressing ovarian (cancer) cells, potentiates the antiproliferative effect of CX-5461." (PMID 29435159, 2018). "The c-MYC oncogene (herein referred to as MYC) is an important driver of neoplastic transformation and is implicated in the pathogenesis of a wide variety of human cancers." (PMID 30453475, 2018). "For example, we have proposed that WBM site inhibitors may have utility as anti-cancer agents, by virtue of their ability to block the MYC–WDR5 interaction, thwarting MYC function in cancer cells." (PMID 29385767, 2018). "Since FOXP3, miR‐198 and MYC do not only exist in liver cells, whether this study could be repeated in other types of cancers remains unclear." (PMID 30378283, 2018). "We then asked whether the observed elevated anti-cancer efficacy after co-exposure to ponatinib and JQ1 or dBET1 is associated with stronger suppression of MYC oncogene expression." (PMID 29899872, 2018). "We noticed that, although identified independently, several of these aberration hubs were connected together through protein-protein interactions and formed a protein network that included several known cancer driver factors such as MYC, EGFR, PIK3C2B, CDK1, and KDR." (PMID 29861861, 2018). "Therefore, targeting glutamine metabolism for MYC-driven tumors is a promising strategy for cancer therapy." (PMID 29371588, 2018). "c-MYC-dependent transcriptional activation through E-box located upstream of the transcription start site also accounted for elevated expression of the oncogenic lncRNA HOTAIR in human cancer." (PMID 29739426, 2018). "MYC is a known oncogene and is highly expressed in a wide variety of cancer types." (PMID 30365520, 2018). "To apply our hypothesis that CLK2‐high and MYC‐amplified cancers were more sensitive to T‐025 in clinical stratification, we re‐assessed the result of our growth inhibition panel on the basis of original organ type and evaluated public clinical data." (PMID 29769258, 2018). "MYC is a transcription factor involved in cell cycle regulation which is dysregulated in many cancers and the H2A.Z.1 gene promoter contains several MYC transcription factor binding sites implicating c-MYC binding as a possible mechanism to facilitate increased cell levels of H2A.Z.1 deposition." (PMID 30651935, 2018). "Therefore, small compounds, designed to stabilize c-MYC quadruplex often encounter off-target effects and narrow therapeutic window limiting their anti-cancer activities." (PMID 30239898, 2018).
cancer (continued). "Therefore, inhibition of the spliceosome in MYC‐driven tumors has been suggested as an adequate pharmacological intervention in cancer." (PMID 29789342, 2018). "Constitutive activation of c-MYC is frequently found in human cancer." (PMID 30603053, 2018). "Another hypothesis is that CLK2 and MYC cooperatively regulate pre‐mRNA biosynthesis and maturation to improve the survival of cancer cells." (PMID 29769258, 2018). "Several previous studies demonstrated that BRD4 could regulate MYC gene transcription and that JQ1 effectively suppresses cancer cell proliferation by inhibiting BET-mediated regulation of MYC in various types of cancer." (PMID 29796168, 2018). "MYC has protean transformational effects upon cells with cancer specific patterns." (PMID 29880060, 2018). "Regulation of c-Myc by AZ2 and polyamines is a novel connection between the MYC signaling and polyamine metabolism, and might be a potential therapeutic target for controlling cancer." (PMID 29445227, 2018). "Intriguingly, MYC‐driven cancers present vulnerability against spliceosome inhibition." (PMID 29789342, 2018). "The well-known cancer target TF include MYC, the ETS family, STAT, Fos, Jun, Myb, Sox2 and more." (PMID 29970794, 2018). "Given the broad implication of MYC protein in human cancers, its myriad functions inside the cell and its regulation at both the transcriptional and post-transcriptional levels by a number of signalling pathways, it seems an excellent candidate to pioneer field cancerisation." (PMID 30619451, 2018). "Importantly the MYC network has been shown to be deeply involved in a broad spectrum of human and other animal cancers." (PMID 30054853, 2018). "To examine whether an increased MYC‐activity rendered cancer cells more sensitive to T‐025, we asserted the effect of MYC activation using SK‐MEL‐28 cells with doxycycline (Dox)‐inducible MYC expression." (PMID 29769258, 2018). "Oncogenes such as BRAF and MYC, through multifaceted shaping of central carbon metabolism and mitochondrial activity, can dictate the propensity of cancer cells to rely on specific metabolic routes such as glycolysis and glutaminolysis, thus revealing susceptibilities to metabolic drugs." (PMID 29629336, 2018). "In cancer biology, c-MYC earned a formidable oncogenic reputation due to its aberrant expression through constitutive transcription, which attributes to autonomous proliferation, chromosomal translocation, relentless replication, and impaired apoptosis in a myriad of cancers." (PMID 30239898, 2018). "The anticancer effects of JQ1 are mediated by MYC down-regulation in many types of cancer." (PMID 29796168, 2018). "Indeed, ABT737 can act as an anti-cancer prophylactic in the Eμ-MYC mouse model of B-cell lymphoma, which has been shown to be dependent on BCL-XL." (PMID 29769323, 2018). "Depletion of USP28 in some cancer cell lines phenocopies the effect of MYC depletion." (PMID 29415985, 2018). "KRAS and MYC have been extensively studied with regard to cancer." (PMID 30788462, 2018). "Based on these observations, we screened the best peptide candidate having higher intracellular selectivity to c-MYC quadruplex and determined its mode of action to drive apoptotic signalling in cancer cells by monitoring differential expression of the apoptotic markers." (PMID 30239898, 2018). "Alternatively, therapeutically targeting the principal oncogenic outputs of hyperactivated MYC, such as those driving protein synthesis, may provide an alternative anti-cancer approach." (PMID 29799508, 2018). "Several groups have asked if there are specific lncRNAs regulated by MYC that could play a role in cellular and cancer physiology." (PMID 28704924, 2017). "Furthermore, MYC was regarded as an independent predictor of progression-free and cancer-specific survival." (PMID 29084575, 2017).
cancer (continued). "In this dynamic scenario, MYC-Mediated Cell Competition (MMCC) may emerge as a cancer trait priming clonal selection and expansion, thus contributing to the final cell composition and mass dimensions." (PMID 28974715, 2017). "Furthermore, TXNIP expression is controlled by various transcriptional regulators like MondoA/MLX, MYC, and HIF1α, and is shown to be silenced in many cancers." (PMID 28124999, 2017). "Given that rapidly proliferating cancer cells, which naturally produce oncogenic MYC, accumulate more genomic instability, it is logical to assume that late-stage or recurrent cancer cells, which are expected to carry high levels of MYC, must have accumulated more DNA damage." (PMID 28590415, 2017). "It is very likely that the NSD3–NUT fusion may be critical for maintenance of MYC expression in these cancer cells." (PMID 28205554, 2017). "However, how the HAT complexes participate in MYC function during cancer development remains uncharacterized." (PMID 29321817, 2017). "Suppression of MYC in cancer cell lines reduces cell viability." (PMID 28152508, 2017). "In addition, pharmacological “tool compound” inhibitors of LDH-A, GLS or lactate exporter MCT1 have been shown to inhibit MYC-dependent tumorigenesis in mouse models of cancer." (PMID 28443281, 2017). "These segments contain known cancer genes including MYC, EGFR, ERBB2 CDKN2A, RB1 and STK11." (PMID 28686671, 2017). "Further studies are needed to verify if these findings also translate into MYC-positive cancers." (PMID 28505071, 2017). "In c-MYC-induced cancers, this delicate balance of c-MYC regulation is lost." (PMID 28379189, 2017). "The pro-oncogene c-MYC is one of the genes most frequently involved in cancer pathogenesis." (PMID 29029460, 2017). "Hence, inhibiting enhanced protein synthesis is a plausible strategy for treating MYC-driven human cancers." (PMID 28362357, 2017). "A relatively high frequency of overexpression of MYC was observed in kidney (48%) and colorectal (37%) cancers; of MYCL (variants 1 and 2) in uterine (58%) and breast (40%) cancers; and of MYCN in uterine (58%), liver (44%), and ovarian (43%) cancers." (PMID 28377632, 2017). "MYC-dependent pathways are often elevated in acquired resistance to anti-cancer therapies." (PMID 28696357, 2017). "BET proteins function as transcriptional regulators of MYC, and their inhibitors disrupt the interaction between BET proteins and MYC, which may result in reduced cell proliferation in cancer." (PMID 28362357, 2017). "The expression of MYC in tumors was 2.8 times higher than in para-cancer tissues (P < 0.01)." (PMID 29084575, 2017). "MYC activity in cancer cells may thus represent a plastic readout of their aberrant gene expression, on the basis of which cells measure their ability to compete in the changing context." (PMID 28974715, 2017). "This increased understanding of MYC's role in control of metabolic machinery has conceived new ideas and concepts for rational design of therapeutic synthetic lethal strategies to treat cancer." (PMID 28443281, 2017). "Mechanistically, MBZ can modulate several cancer-associated pathways, such as ELK1/SRF, AP1, STAT1/2, MYC/MAX, although the regulatory outcomes may be context-dependent." (PMID 28099902, 2017). "Significant role of MYC in the various pathways of cancers is studied and confirmed." (PMID 29511483, 2017). "Finally, MYC is a well-known transcription factor that plays a central role in cancer development processes including cell proliferation, growth, and apoptosis." (PMID 28443095, 2017). "Fundamental to MYC’s impact on both normal development and cancer cell physiology is a potent capacity to promote cell and tissue growth through activation of the genes necessary for protein synthesis for accumulation of cellular biomass and cell cycle machinery to drive proliferation." (PMID 28398229, 2017).
cancer (continued). "The tendency for higher IR in cancer cells might be related to the apparent vulnerability of the spliceosome in MYC transformed cells, as indicated by synthetic lethality between MYC transformation and knockdown of core splicing factors." (PMID 28391524, 2017). "MYC proteins have also proven to trigger non cell-autonomous responses at the tissue/organ level which deeply impact cancer outcome, according to the emerging vision of cancer as a social network of interplaying cells." (PMID 28974715, 2017). "Given its double function in cell elimination and replacement, MYC-mediated CC may thus represent one of the forces driving both clonal culling and dominance during cancer progression." (PMID 28420161, 2017). "Additionally, the lncRNA colon cancer-associated transcript 2 (CCAT2) enhances WNT activity by binding to TCF7L2, a pivotal transcription factor in the WNT signalling pathway, and facilitates MYC activity, thereby enhancing cancer cell invasion and metastasis." (PMID 29137343, 2017). "Further investigation of these cancer driver genes will be required to reveal novel insights into MYC biology and answer the question whether MYC or MYC's target genes can be targeted for cancer therapy." (PMID 28152508, 2017). "MYC and Wnt signaling pathways are key importance for cancer and stem cell biology." (PMID 28740573, 2017). "Solid demonstration of the clinical feasibility of any MYC-based synthetic lethal strategy still awaits to come forth but it is important to note that at general level, the concept of attacking cancer metabolic vulnerabilities has been fully validated in the clinic." (PMID 28443281, 2017). "To support this hypothesis, we co-cultured pairs of different human cancer cell lines demonstrating that, whatever the genotype of the cells, MYC protein modulation was sufficient to subvert their competitive behaviour." (PMID 28974715, 2017). "By analysis of the mice, we found that the entire super-enhancer region conferring multi-cancer susceptibility contributes to MYC expression in vivo, yet is not required for mouse embryonic development and viability." (PMID 28583252, 2017). "MYC is involved in the tumorigenesis of several cancer entities including RT." (PMID 29156698, 2017). "Therefore, our results add to the current knowledge and suggest a multifaceted regulation of c‐MYC at different levels by AURKA in cancer." (PMID 28417568, 2017). "Indeed, FAM83A is located next to c-MYC at the chromosomal locus 8q24, which is often amplified in cancers." (PMID 28463969, 2017). "Given that MYC participates in transcriptional reprogramming that facilitates the creation of iPS cells from differentiated cells, it may be possible for MYC-overexpressing cancer cells to acquire traits similar to those of cancer-stem cells." (PMID 28590415, 2017). "We propose that upregulation of the γH2AX-inducing factor (such as ATM) by MYC in cancer cells might result in persistent formation of γH2AX foci, which serves as a pseudo-positive DSB signal that sustains the activation of DNA-repair machinery." (PMID 28590415, 2017). "Here, TR refers to global repression of transcription rather than specific targeting of cancer-causing genes such as MYC." (PMID 28454100, 2017). "Recently, novel therapeutic strategies have emerged that promise to take advantage of the reversibility of chromatin modifications to adjust the epigenome in ways that slow cell proliferation and induce cellular senescence or apoptosis in MYC-deregulated cancers." (PMID 28505071, 2017). "In many other cancers, the region surrounding MYC is subject to gene amplification." (PMID 28704924, 2017). "Moreover, we demonstrated that, by transcriptionally promoting the expression of MYC target genes in cancer cells, Menin stimulates cell proliferation, cellular metabolism and cancer progression." (PMID 28474697, 2017).